GNB1 (G protein subunit beta 1)
Description:
Guanine nucleotide-binding proteins (G proteins) are involved as a modulator or transducer in various transmembrane signaling systems. The beta and gamma chains are required for the GTPase activity, for replacement of GDP by GTP, and for G protein-effector interaction.
Synonyms: HG2A; MDS; MRD42
Tractability: Small molecule: a structure with a bound ligand is known; a high-quality ligand is known. Antibody: its Gene Ontology location is reachable by antibodies, with high confidence; the Human Protein Atlas places it where antibodies can reach. PROTAC: ubiquitination databases record sites on it; its protein half-life has been measured; a small molecule that binds it is known.
Gene: Protein-coding gene on chromosome 1 (1,785,285 to 1,892,292, reverse strand). Ensembl gene ENSG00000078369.
Subcellular location (Human Protein Atlas): Plasma membrane; Golgi apparatus
Pathways (Reactome):
Signal Transduction: Ca2+ pathway; Extra-nuclear estrogen signaling; G alpha (12/13) signalling events; G alpha (i) signalling events; G alpha (q) signalling events; G alpha (s) signalling events; G alpha (z) signalling events; G beta:gamma signalling through BTK; G beta:gamma signalling through CDC42; G beta:gamma signalling through PI3Kgamma; G beta:gamma signalling through PLC beta; G-protein activation; GPER1 signaling; Glucagon-type ligand receptors
Hemostasis: ADP signalling through P2Y purinoceptor 1; ADP signalling through P2Y purinoceptor 12; Prostacyclin signalling through prostacyclin receptor; Thrombin signalling through proteinase activated receptors (PARs); Thromboxane signalling through TP receptor
Sensory Perception: Activation of the phototransduction cascade; Inactivation, recovery and regulation of the phototransduction cascade; Olfactory Signaling Pathway; Sensory perception of sweet, bitter, and umami (glutamate) taste
Metabolism: Adrenaline,noradrenaline inhibits insulin secretion; Glucagon signaling in metabolic regulation; Glucagon-like Peptide-1 (GLP1) regulates insulin secretion
Neuronal System: Activation of G protein gated Potassium channels; Inhibition of voltage gated Ca2+ channels via Gbeta/gamma subunits; Presynaptic function of Kainate receptors
Metabolism of proteins: Cooperation of PDCL (PhLP1) and TRiC/CCT in G-protein beta folding; Synthesis, secretion, and inactivation of Glucagon-like Peptide-1 (GLP-1)
Cellular responses to stimuli: High laminar flow shear stress activates signaling by PIEZO1 and PECAM1:CDH5:KDR in endothelial cells
Disease: ADORA2B mediated anti-inflammatory cytokines production
Transport of small molecules: Vasopressin regulates renal water homeostasis via Aquaporins
Gene Ontology:
Molecular function: GTPase activity; GTPase binding; protein binding; protein-containing complex binding; signaling receptor complex adaptor activity
Biological process: adenylate cyclase-activating dopamine receptor signaling pathway; cellular response to catecholamine stimulus; cellular response to prostaglandin E stimulus; G protein-coupled acetylcholine receptor signaling pathway; G protein-coupled receptor signaling pathway; Ras protein signal transduction; signal transduction
Cellular component: extracellular exosome; extracellular vesicle; heterotrimeric G-protein complex; lysosomal membrane; plasma membrane; cytosol; membrane; photoreceptor disc membrane; photoreceptor outer segment; synapse
Genetic constraint (gnomAD): Loss-of-function variants: 0 observed, 13.47 expected, observed/expected ratio (o/e) 0, 90% interval 0 to 0.22. The upper end of that interval is the gene's LOEUF score, 0.22, which puts it in group 1 of 6, group 1 being the genes least tolerant of losing a copy. Missense variants: 95 observed, 244.19 expected, observed/expected ratio (o/e) 0.39, 90% interval 0.33 to 0.46. Synonymous variants: 92 observed, 98.46 expected, observed/expected ratio (o/e) 0.93, 90% interval 0.79 to 1.11.
Gene-disease validity (ClinGen):
ClinGen rates the evidence that GNB1 causes each of these diseases.
intellectual disability, autosomal dominant 42 (autosomal dominant): Definitive. Any autosomal dominant intellectual disability in which the cause of the disease is a heterozygous mutation in the GNB1 gene.
Homologues: Orthologues: chimpanzee GNB1 (100% identical), guinea pig GNB1 (100% identical), macaque GNB1 (100% identical), mouse Gnb1 (100% identical), rabbit GNB1 (100% identical), rat Gnb1 (100% identical), zebrafish gnb1b (98% identical), tropical clawed frog gnb1 (97% identical), dog GNB1 (91% identical), pig GNB1 (91% identical), Caenorhabditis elegans gpb-1 (86% identical), Drosophila melanogaster Gbeta13F (84% identical). Paralogues in human: GNB4 (91% identical), GNB2 (90% identical), GNB3 (83% identical), GNB5 (53% identical).
Diseases named in the same sentence as GNB1 in open-access papers:
GNB1 is named in the same sentence as 108 diseases in open-access papers, as found by Europe PMC text mining. Sharing a sentence is not in itself a finding about the gene and the disease. The quoted sentences say what the papers report.
developmental delay (13 papers, 2020 to 2025). "Pathogenic variants in GNB1 have been associated with neurodevelopmental disorders involving developmental delay, intellectual disability, and behavioral symptoms, including autism spectrum disorder." (PMID 40873676, 2025). "Mutations in GNB1 have been linked to growth and (neuro)developmental delay, and gastrointestinal problems." (PMID 39971893, 2025). "Mutations in GNB1 have been associated with developmental delay, hypotonia, and various behavioral disorders." (PMID 40873676, 2025). "The heterozygous pathogenic GNB1 variant in the 1p36.33 region leads to GNB1 encephalopathy, which manifests as moderate-to-severe developmental delays, intellectual disability, or structural brain abnormalities." (PMID 38280885, 2024). "Recent studies have shown that heterozygous germline mutations in GNB1 (in more than 100 patients to date), the gene encoding the Gβ1 subunit, lead to developmental delay, autism-like symptoms, seizures, and hypotonia." (PMID 38732215, 2024). "De novo mutations in GNB1, encoding the Gβ1 subunit of G proteins, cause a neurodevelopmental disorder with global developmental delay and epilepsy, GNB1 encephalopathy." (PMID 37275776, 2023). "Global developmental delay and subsequent moderate to severe intellectual disability are observed in almost all patients with GNB1, GNAO1, PDE2A, and HPCA variants." (PMID 36003298, 2022). "De novo pathogenic variants in GNB1 have been associated with many neurological diseases, such as developmental delay, dystonia, growth delay and seizures." (PMID 35310542, 2021). "Here, we present two additional patients with a reported likely pathogenic variant and a variant of uncertain significance in GNB1, and phenotypes including developmental delay, intellectual disability, hypotonia, and psychiatric symptoms." (PMID 32918542, 2020). "Mutations in this gene can lead to neurodevelopmental disorders in the head region, including global developmental delay and epilepsy, resulting in GNB1 encephalopathy." (PMID 40278589, 2025). "In conclusion, behavioral phenotypes in Gnb1K78R/+ mice on the NJ background might be relevant to understanding GNB1 encephalopathy, which includes global developmental delay, ambulatory deficits, and intellectual disability." (PMID 37275776, 2023). "Dominant mutations in GNAO1, GNB1, and PDE2A have been associated to a complex early-onset neurological disorder characterized by a variable association of hyperkinetic MD, epilepsy, and developmental delay generally evolving into intellectual disability." (PMID 36003298, 2022). "In addition, a growing number of genes initially linked to other neurological phenotypes, such as developmental delay, epilepsy, or ataxia, are now recognized to cause prominent dystonia, occasionally in an isolated fashion (e.g., GNAO1, GNB1, SCN8A, RHOBTB2, and COQ8A)." (PMID 36705216, 2022). "Interestingly, the deletion of patient 32, encompassing partly GNB1, is reported with dysmorphism, seizures, hypotonia, myelination delay, ventriculomegaly, and developmental delay without any cardiac malformations." (PMID 36369750, 2023).
epilepsy (12 papers, 2017 to 2025). A brain disorder characterized by episodes of abnormally increased neuronal discharge resulting in transient episodes of sensory or motor neurological dysfunction, or psychic dysfunction. "Importantly, mutations of Cask, Hrnrpu and Gnb1 genes have been associated to neurodevelopmental syndromes characterized by intellectual disability and epilepsy." (PMID 30687010, 2018). "Preclinical studies are needed to understand the pathophysiology of epilepsy in GNAO1 and GNB1 deficiency and to clarify the role of the mTOR signaling pathway activation." (PMID 36003298, 2022). "Epilepsy can be prominent in GNB1 and GNAO1 encephalopathy, while it is anecdotical in individuals with HPCA, PDE2A, and PDE10A pathogenic variants." (PMID 36003298, 2022). "The brown module has 53 hub genes, including genes associated with dopaminergic signaling (GNB1, GSK3B), long-term potentiation (PPP1CB), opioid signaling (PPP2CA, PPP3CA, PPP3R1), epilepsy (SYN1), and Parkinson’s disease (SNCA)." (PMID 28710498, 2017). "We believe that such high levels of methylation observed in the GNB1-seizure associated locus possibly indicates epigenetically driven regulation of GNB1, but also note that its relevance for neurological phenotypes in epilepsy (like seizures) currently remains unknown." (PMID 41345172, 2025). "First, though we have reported strong evidence of CNV-seizure activity in GNB1, these results are not yet applicable for clinical translation in epilepsy patients." (PMID 41345172, 2025). "It is not clear how GNB1 mutations that cause both GoF (K78R) and LoF (I80T/N) toward GIRK activation can cause epilepsy." (PMID 37275776, 2023). "This work implicates a GoF mechanism for GIRK channels in epilepsy, identifies a new mechanism of action for ETX in preventing seizures, and establishes this mouse model as a pre-clinical tool for translational research with predicative value for GNB1 encephalopathy." (PMID 37275776, 2023). "While the clinical phenotype associated with ADCY5 and GNAL is characterized by movement disorder in the absence of epilepsy, GNAO1, GNB1, PDE2A, PDE10A, and HPCA have a broader clinical phenotype, encompassing movement disorder, epilepsy, and neurodevelopmental disorders." (PMID 36003298, 2022).
lung carcinoma (11 papers, 2016 to 2025). "miR-326 mediates the inhibition of lung cancer cell stemness by suppressing GNB1, which supported the stemness of lung cancer cells." (PMID 39170516, 2024). "By sponging miR-326, circPOLA2 performs the role of a ceRNA and controls GNB1 expression in lung cancer cells." (PMID 39170516, 2024). "Contribution to lung cancer stemness was reported for circ_POLA2 via miR-326/GNB1 axis, where the circ_POLA2 was highly expressed in lung cancer tissues and predicted a poor prognostic outcome." (PMID 38501058, 2024). "We discovered that many lncRNAs were located nearby important key regulators of lung cancer, including FN1, PCNA, BUB1, GNB1, and other cancer associated genes." (PMID 26918601, 2016). "In lung cancer, increased circ_0003998 and circ_POLA2 regulate cell proliferation and invasion, resulting in a poor survival rate in lung cancer patients relying on miR-326, which suppresses its target genes, Notch1 and GNB1." (PMID 36769372, 2023). "Interestingly, GNB1 is depicted as a tumor suppressor in clear cell renal cell carcinoma, although it is an oncogenic protein in lung cancer and cervical squamous cell carcinoma." (PMID 35193469, 2022). "In addition, GNB1 is highly expressed in lung cancer and promotes the viability of lung cancer cells in vitro." (PMID 35193469, 2022). "Furthermore, circular RNA_POLA2 accelerates the dryness of lung cancer cells via modulating the miR-326/GNB1 axis." (PMID 35192430, 2022). "Further, through thousands of protein screenings, we identified four proteins (MYH9, GNB1, ALOX12B, HSD17B4) that can predict the response to MET inhibitors for MET-dysregulated lung cancer patients." (PMID 36612298, 2023). "Depletion of circPOLA that acts as a sponge for miR-326 with the subsequent upregulation of the G protein subunit beta 1 (GNB1) expression leads to reduction of sphere formation ability, ALDH1 activity, and stemness marker expression of lung cancer cells." (PMID 36338714, 2022).
Encephalopathy (8 papers, 2021 to 2025). Encephalopathy is a term that means brain disease, damage, or malfunction. "Previous studies have shown that GNB1 encephalopathy can cause neurodevelopmental disorders by altering the signaling of potassium (GIRK) channels; moreover, as a member of the Gβ subunits, GNB1 can form a dimer with the Gγ subunit." (PMID 40278589, 2025). "GNB1 encephalopathy is a rare genetic disease caused by pathogenic variants in the G Protein Subunit Beta 1 (GNB1) gene, with only around 68 cases documented worldwide." (PMID 38674235, 2024). "In a recent study, inspired by the results of the present article published on a preprint server, we investigated the effects of three GNB1 mutations seen in patients with GNB1 encephalopathy—K78R, I80N, and I80T—in heterologous expression systems." (PMID 37275776, 2023). "We describe the first mouse model of GNB1 encephalopathy carrying the pathogenic missense variant K78R." (PMID 37275776, 2023). "Our results indicate that the K78R mutation identified in individuals with GNB1 encephalopathy affects cortical network activity and suggests that GoF of GIRK activation is an important part of the underlying mechanism." (PMID 37275776, 2023). "In conclusion, we reported an additional GNB1 encephalopathy patient, bearing a novel mutation, taking another step toward a better understanding of its clinical presentation and prospective development of treatments for the disease." (PMID 34646230, 2021). "It is particularly important for lysine 78, a residue whose mutation (K78R) was already identified as causal of GNB1 encephalopathy." (PMID 34646230, 2021). "Pathogenic variants in GNB1 cause a heterogeneous neurodevelopmental syndrome named GNB1 encephalopathy (OMIM: 616973) whose unifying characteristic is a global development delay (GDD), present in 100% of patients." (PMID 34646230, 2021). "Gnb1K78R/+ mice phenocopy many aspects of GNB1 encephalopathy, including developmental delay and motor and cognitive deficits, as well as abnormal neuronal excitability." (PMID 37275776, 2023). "We have described a new case of GNB1 encephalopathy, namely a patient with profound GDD, ID and a complex behavioral disorder." (PMID 34646230, 2021). "The detected variant (c.217G>A, p.A73T) has not been previously reported in any of the 58 published cases of GNB1 encephalopathy." (PMID 34646230, 2021). "In this regard, it is relevant to mention patients with GNB1 encephalopathy, in whom paroxysmal dyskinesias lasting for hours may be observed, usually triggered by fever and related to awakening." (PMID 38903163, 2024). "Overall, we present the first animal model of GNB1 encephalopathy, with several phenotypes relevant to clinical features and thereby representing a tool for translational research, and we implicate GIRK channels as an important component of how GNB1 mutations cause disease." (PMID 37275776, 2023). "In conclusion, we have described a case of GNB1 encephalopathy with a de novo mutation which affects a residue that has not been previously implicated in disease." (PMID 34646230, 2021). "As there are no standardized GNB1 encephalopathy treatment guidelines, evaluation of different treatment options is based on anecdotal cases." (PMID 38674235, 2024). "Although the patient’s symptoms are characteristic for GNB1 encephalopathy, they are not specific for this disease, especially as the patient exhibits a mild phenotype." (PMID 38674235, 2024). "Language impairment can be profound, especially in GNAO1 and GNB1 encephalopathy, and it is not clear if it is related to the prominent oromandibular distribution of movement disorders, or if it depends on cognitive impairment with or without oral dyspraxia." (PMID 36003298, 2022).
Dystonia (7 papers, 2020 to 2025). An abnormally increased muscular tone that causes fixed abnormal postures. "The case in mention has many similarities with the case we are reporting; in both cases, the GNB1 variant phenotype is mild and age of onset for dystonia and myoclonus is similar." (PMID 38674235, 2024). "Movement disorder is frequent in patients with GNB1 pathogenic variants (23 individuals), usually dystonia and/or ataxia." (PMID 36003298, 2022).
Intellectual disability (6 papers, 2018 to 2025). "Here, we report two patients with functionally confirmed loss of function variants in GNB1 and neurodevelopmental phenotypes including intellectual disability, hypotonia, and seizures in one patient." (PMID 32918542, 2020). "In summary, we present two patients with novel LoF variants in GNB1 and neurodevelopmental phenotypes including intellectual disability, hypotonia, obesity, as well as seizures, and psychiatric symptoms in one patient." (PMID 32918542, 2020).
breast carcinoma (4 papers, 2014 to 2022). "GNB1 is augmented in breast cancer (BC) and is positively associated with mammalian target of rapamycin." (PMID 35192430, 2022). "Guanine nucleotide binding protein (G protein), beta polypeptide 1 (GNB1) has been recently found to be associated with breast cancer outcomes and clinical and pathological measurements." (PMID 24774302, 2014). "G protein subunit beta 1 (GNB1), which is a novel transduction protein, has been demonstrated to play a critical role in breast cancer." (PMID 32766125, 2020). "Furthermore, GNB1 is provided with a potential targeting in human breast cancer (HBC) therapy." (PMID 35192430, 2022).
Obesity (4 papers, 2017 to 2025). Accumulation of substantial excess body fat. "The results revealed that 18 of the DMR genes were associated with addiction and obesity (ADCY3; ADCY9; ATF4; CDK5R1; CHRNB2; GABRD; GABRG3; GNB1; GNB3; GRK5; HDAC4; HDAC9; MAP2K1; PDE11A; PDE2A; PDE3A; PPP1CA; SLC6A3)." (PMID 34389046, 2021). "This study integrates proteomic data on adipocyte fat accumulation with GWAS data on obesity to unravel the roles of the identified key candidate genes — G protein subunit beta 1 (GNB1) and scavenger receptor class B member 2 (SCARB2) — involved in fat accumulation." (PMID 40127054, 2025). "The identification of GNB1 and SCARB2 as potential regulators in human subcutaneous adipocytes underscores their importance in obesity-related processes, such as fat accumulation." (PMID 40127054, 2025). "Our findings highlight the significant roles of GNB1 and SCARB2 in lipid metabolism and adipocyte function, providing insights that could inform therapeutic strategies targeting these regulatory genes in obesity." (PMID 40127054, 2025).
cervical squamous cell carcinoma (3 papers, 2020 to 2025). A squamous cell carcinoma arising from the cervical epithelium. "GNB1 is a target gene of miR-326 that promotes malignant phenotypes in lung and cervical squamous cell carcinoma and is positively regulated by circ_POLA2." (PMID 35193469, 2022). "Moreover, other studies have shown that GNB1 is overexpressed in cervical squamous cell carcinoma, which predicts poor prognosis in patients." (PMID 35193469, 2022). "In conclusion, circ_POLA2 promotes cervical squamous cell carcinoma development and progression via regulating the miR-326/GNB1 axis, which might serve as a novel therapeutic target for CESC patients." (PMID 32766125, 2020).
Cognitive impairment (3 papers, 2022 to 2023). Abnormal cognition is characterized by deficits in thinking, reasoning, or remembering. "In the DOX-RT treated mice, we identified increased expression of genes associated with cognitive impairment, namely Adar, Gnb1, and Vim." (PMID 38248237, 2023).